XBP1 (X-box binding protein 1)
Diseases named in the same sentence as XBP1 in open-access papers (continued):
Sharing a sentence is not in itself a finding about the gene and the disease.
acute kidney injury (6 papers, 2016 to 2025). Sudden and sustained deterioration of the kidney function characterized by decreased glomerular filtration rate, increased serum creatinine or oliguria. "In conclusion, our findings identify BRD4 as a key regulator of overexpression of the ATF4 and XBP1 UPR genes after acute kidney injury induced by IRI." (PMID 38481808, 2024). "Similarly, XBP1 via Hrd1 has been shown to modulate the antioxidant function of Nrf2 in ischemia-reperfusion induced acute kidney injury." (PMID 35350536, 2022). "The classical ER stress response protein XBP1 participates in the crosstalk between ER stress and mitochondrial dysfunction by upregulating HRD1 expression, consequently contributing to the development of acute kidney injury." (PMID 38378757, 2024). "However, the role of XBP1, a crucial regulator of adaptive UPR, remains unclear during the transition from acute kidney injury (AKI) to chronic kidney disease (CKD)." (PMID 35765067, 2022).
pulmonary fibrosis (6 papers, 2019 to 2024). Chronic progressive interstitial lung disorder characterized by the replacement of the lung tissue by connective tissue, leading to progressive dyspnea, respiratory failure, or right heart failure. "Our study is the first to reveal that the pathogenesis of CSE regulates LINC00665/XBP-1 in the process of pulmonary fibrosis." (PMID 38111802, 2023). "Our study attempted to elucidate the possible mechanism by which CSE regulates LINC00665/XBP-1 in the process of pulmonary fibrosis through cell and animal experiments." (PMID 38111802, 2023). "In addition, melatonin attenuates BLM‐induced pulmonary fibrosis by decreasing the expression of p‐IRE1α and its downstream target XBP1 to activate JNK." (PMID 39056330, 2024). "Taken together, these results indicated that MSCs attenuated ER stress and EMT in the lungs of mice with lung fibrosis and that suppression of the IRE1α/XBP1 pathway may play a critical role in this effect." (PMID 37545482, 2023). "Therefore, we explored and verified the mechanism by which cigarette smoke exposure (CSE) regulates LINC00665/XBP-1 involvement in pulmonary fibrosis through cell experiments." (PMID 38111802, 2023). "Our results showed that CSE regulates LINC00665/XBP-1, which may play an important role in the process of pulmonary fibrosis and may become a new target for IPF treatment." (PMID 38111802, 2023). "Here, we investigated whether ER stress contributes to lung fibrosis following MERS-CoV infection by analyzing the levels of ER-stress-associated genes, such as Perk, Atf4, Chop, Atf6, and X-box binding protein 1 (Xbp1) in the lungs of MERS-CoV-infected hDPP4-Tg mice and sham-infected hDPP4-Tg mice." (PMID 33139653, 2020). "In this study, we aim to ascertain the relationship between smoking, pulmonary fibrosis, LINC00665, and XBP-1." (PMID 38111802, 2023). "We clarified the mechanism between LINC00665 and XBP-1 through cellular and molecular experiments, and verified the inhibitory effect of silencing LINC00665 on pulmonary fibrosis by using a bleomycin (BLM)-induced pulmonary fibrosis model." (PMID 38111802, 2023). "Next, in the mice model of pulmonary fibrosis, we confirmed that CSE positively regulates LINC00665/XBP-1 to participate in the lung fibroblast-to-myofibroblast transition and that LINC00665 regulates XBP-1 by negatively regulating miR-214-3p." (PMID 38111802, 2023). "In our study, we explored the mechanism of CSE on LINC00665 and XBP-1 in lung fibroblast-to-myofibroblast transition, confirmed the interaction between LINC00665 and XBP-1, and observed the inhibitory effect of silencing LINC00665 on pulmonary fibrosis in mice." (PMID 38111802, 2023). "In addition, XBP-1 has been identified as a target of miR-214-3p, so XBP-1 could be regulated by LINC00665 to act on the process of pulmonary fibrosis." (PMID 38111802, 2023). "However, the specific cellular and molecular mechanism of XBP-1 in pulmonary fibrosis is not very clear, and more clinical studies are needed to explore the relationship between XBP-1 and the decline in IPF pulmonary function." (PMID 38111802, 2023). "However, the regulatory role of cigarette smoke exposure (CSE) on LINC00665/XBP-1 in the process of pulmonary fibrosis has not been officially reported." (PMID 38111802, 2023).
schizophrenia (6 papers, 2009 to 2025). A major psychotic disorder characterized by abnormalities in the perception or expression of reality. "Several studies have investigated the association between ER stress and schizophrenia due to genetic factors, including X-box-binding protein 1 (XBP-1) 116C/G and 197C/G." (PMID 40943517, 2025). "XBP1 splicing is considered an important marker of ER stress and has been implicated in the pathogenesis of schizophrenia." (PMID 37376599, 2023). "The three major UPR pathways are directly or indirectly linked to ATF6, with XBP1, a risk factor for schizophrenia, being a downstream target gene of ATF6." (PMID 37376599, 2023). "Of these, genetic variants of XBP1 have also been linked to schizophrenia." (PMID 38199991, 2024). "Taken together, ATF6, BCL-2, and ERVW-1 displayed a significant correlation with XBP1 in schizophrenia." (PMID 37376599, 2023). "In conclusion, ERVW-1 induced ER stress by suppressing GANAB expression, thereby upregulating the expression of ATF6 and XBP1 and ultimately contributing to the development of schizophrenia." (PMID 37376599, 2023). "These molecular signatures suggest that ATF6 and XBP1 may serve as biomarkers and functional contributors to schizophrenia." (PMID 41473415, 2025). "Furthermore, we visualized the multiple correlations and regression analyses among ERVW-1, GANAB, ATF6, and XBP1 in the serum of individuals with recent-onset schizophrenia (n = 39) using a heatmap." (PMID 37376599, 2023). "In this paper, we found that ATF6 and XBP1 could be potential serum biomarkers of schizophrenia." (PMID 37376599, 2023). "As expected, we found a significant positive correlation between XBP1 and BCL-2 in schizophrenia (R2 = 0.58)." (PMID 37376599, 2023). "Subsequent research indicated that the UPR gene called XBP1 had a positive correlation with ATF6, BCL-2, and ERVW-1 in individuals with schizophrenia using Spearman correlation analysis." (PMID 37376599, 2023). "In summary, there was aberrant expression of ATF6, XBP1, and GANAB in the serum of schizophrenic patients, and these proteins displayed significant correlations with ERVW-1 in schizophrenia." (PMID 37376599, 2023). "Interestingly, previous studies have reported that ATF6 induces XBP1 mRNA, which aligns with our findings of a positive correlation between ATF6 and XBP1 in the bioinformatic analysis and correlation analysis in schizophrenia." (PMID 37376599, 2023). "Interestingly, in GSE21138, ERVW-1 exhibited a significant positive correlation with XBP1 at the transcriptional level in the prefrontal cortex of individuals with schizophrenia, suggesting a connection among ERVW-1, ATF6, and XBP1." (PMID 37376599, 2023). "Therefore, we propose that ATF6, XBP1, and GANAB might serve as potential serum biomarkers of schizophrenia." (PMID 37376599, 2023).
type 1 diabetes (6 papers, 2015 to 2023). "In the present study, we investigated how the loss of XBP1 affects the function and morphology of the retina in a mouse model of type 1 diabetes." (PMID 31242599, 2019). "The modified cells were then exposed to proinflammatory cytokines mimicking the pathogenic inflammatory beta cell microenvironment of pancreatic islet in type 1 diabetes, i.e. IFNγ/IL1β or IFNγ/IL1β/TNFα and analysed for endogenous XBP1 splicing by qPCR or light emission in cell lysates." (PMID 30532033, 2018). "The purpose of this study is to determine the role of XBP1-mediated UPR in retinal neuronal survival and function in a mouse model of type 1 diabetes." (PMID 31242599, 2019). "For example, IRF7 (the interferon regulatory factor 7) driven regulatory cascade in which genetic variation on chromosome 15q25 leads to type 1 diabetes (pathway: 04940) and XBP1 (X-box binding protein 1) induce pancreatic beta cell dysfunction and apoptosis of type 1 diabetes." (PMID 26688819, 2015).
asthma (5 papers, 2018 to 2024). "An increase in ER stress markers including ATF4, ATF6, CHOP, GRP78, and XBP1 has been detected in those with ovalbumin-induced asthma." (PMID 39295946, 2024). "Here, we investigated the role of the IRE1a-XBP1 pathway in regulating activation and differentiation of type-2 T helper cell (Th2), a major T helper cell type involved in allergy, asthma, helminth infection, pregnancy, and tumor immunosuppression." (PMID 30355343, 2018). "This study shows evidence that perturbation of the IRE1a-XBP1 pathway may interfere with normal physiological activation of Th2 and could be exploited in settings where Th2 lymphocytes are pathologic such as asthma, allergies, and eosinophilia." (PMID 30355343, 2018).
Burkitt lymphoma (5 papers, 2010 to 2023). A rare form of malignant mature B-cell non-Hodgkin lymphoma. "Similarly, pharmacological and genetic inhibition of XBP1 induce c‐Myc‐dependent apoptosis of Burkitt's lymphoma models, which is alleviated by exogenous unsaturated fatty acids." (PMID 32310340, 2020). "To investigate this mechanism in Burkitt’s lymphoma, we examined the expression of downstream effectors of the UPR pathway, including Xbp1, Chop, and Bip, using qPCR." (PMID 37752998, 2023). "Along these lines, another study in Burkitt's lymphoma cells reports that c‐Myc binds the E‐box sequences in the promoters of both ERN1 and XBP1 genes, establishing c‐Myc as a direct upstream regulator of the IRE1α‐XBP1s pathway." (PMID 32310340, 2020). "We found the ratio of spliced to un-spliced XBP1 to be higher in KO cells compared to WT in unstimulated state (almost two folds), which is not a characteristic of Burkitt’s lymphoma." (PMID 32788680, 2020). "In this study, we found that IRE1α/XBP1 axis inhibition exerted a stronger cytotoxic effect compared to the inhibition of the other two UPR sensors, namely PERK and ATF6, in Burkitt lymphoma (BL) cells, in correlation with c-Myc downregulation." (PMID 36012375, 2022).
Cognitive impairment (5 papers, 2016 to 2025). Abnormal cognition is characterized by deficits in thinking, reasoning, or remembering. "Notably, dysregulated PERK/eIF2α and IRE1/XBP1 pathways are implicated in synaptic plasticity deficits, cognitive impairment, and maladaptive neuroinflammation." (PMID 41473415, 2025). "Animal experiments have shown that mice in the A/S group exhibited cognitive impairments accompanied by increased Hspa5 and Xbp1 expression, ER stress, and activation of NLRP3 inflammasome." (PMID 39432407, 2024). "Recent findings showed that ER stress-relevant molecules (e.g. CHOP and Xbp1) are also involved in the pathogenesis of cognitive deficits in both T1DM and T2DM models." (PMID 27793043, 2016). "Anesthesia and surgery‐induced upregulation of Hspa5 and Xbp1 gene expression subsequently led to ER stress, NLRP3 inflammasome activation, and neuroinflammation, potentially contributing to cognitive deficits in aged mice." (PMID 39432407, 2024). "As a result of this inhibition, the splicing of XBP1 and the production of BDNF would be impaired, which might contribute to worsen the cognitive deficits and the inflammatory response in 5xFAD mice." (PMID 39268577, 2024).
endometrial cancer (5 papers, 2018 to 2024). Primary or metastatic malignant neoplasm involving the endometrium (mucous membrane that lines the endometrial cavity). "One recent study indicates that XBP1 potentially distinguishes the polymerase epsilon exonuclease (POLE) from the copy number (CN)-low endometrial cancer subtype." (PMID 37880674, 2023). "For instance, microbial analysis of endometrium from patients with endometrial cancer and healthy volunteers revealed that Prevotella and Pelomonas were enriched in the endometrial cancer group, Prevotella was significantly associated with three genes (PRSS33, CPB2, XBP1)." (PMID 39360320, 2024). "Furthermore, high levels of XBP1 were an independent prognostic factor for improved progression-free survival only in women with endometrial cancer, suggesting that XBP1 plays a distinct role in oestrogen signalling in endometrial cancer." (PMID 32069845, 2020). "PGR (Progesterone receptor), FOXA1 (Forkhead box protein A1), XBP1 (X-box binding protein 1), and TFF1 (Trefoil factor 1) were reported to involve in the estrogen signal in endometrial cancer." (PMID 33324448, 2020). "It was also reported that XBP1 and UHRF1 are related to tumor growth or carcinogenesis in endometrial cancer." (PMID 29642629, 2018). "AR target genes such as XBP1, MYC, ZBTB16, and UHRF1 were previously reported to be induced by DHT treatment in AR-positive endometrial cancer MFE-296 cells." (PMID 29642629, 2018).
endothelial dysfunction (5 papers, 2022 to 2025). In vascular diseases, endothelial dysfunction is a systemic pathological state of the endothelium (the inner lining of blood vessels) and can be broadly defined as an imbalance between vasodilating and vasoconstricting substances produced by (or acting on) the endothelium. "Endoplasmic reticulum stress and subsequent endothelial cell apoptosis, involving activation of eukaryotic initiation factor 2α (EIF2α), X-box-binding protein 1 (XBP1), CCAAT-enhancer-binding protein homologous protein (CHOP), and NF-κB, can induce endothelial dysfunction." (PMID 40093324, 2025).
hyperlipidemia (5 papers, 2021 to 2025). "Hyperlipidemia―IRE1α―XBP1―ER stress―STING―TBK1―NF-κB―pro-inflammatory." (PMID 41153813, 2025).
ileitis (5 papers, 2011 to 2022). "While Xbp1-deficient mice are protected from ileitis in GF housing, colonized Xbp1−/− mice develop spontaneous transmural inflammation, resembling Crohn’s ileitis phenotype in humans." (PMID 26635787, 2015). "Similarly, the ileitis induced after knockout of XBP1 in IECs is rescued by TNFR1 deficiency." (PMID 35077396, 2022). "Further, ATG16L1 deficiency, when found in conjunction with Paneth cell-specific deletion of the gene that codes for X-box binding protein-1 (Xbp1), results in spontaneous ileitis." (PMID 28469609, 2017). "Dysfunctions in either unfolded protein response factor, X‐box binding protein 1 (XBP1), or autophagy (ATG16L1 or ATG7) in IECs result in the reciprocal compensatory, and severe spontaneous ileitis develops if both mechanisms are defective." (PMID 29941542, 2018). "The increased response of the ileum to alterations in the UPR is consistent with the spontaneous development of ileitis in mouse models with deleted XBP1, where the absence of XBP1 prevents its beneficial effect on ER homeostasis and consequently increase the burden on the ER." (PMID 22028783, 2011).
liver disease (5 papers, 2016 to 2024). "In addition, analyses of gene-specific diurnal variations in levels of H3K27ac and H3K9ac of liver disease-driving genes (XBP1 and RAF1) and CC-component CRY1 confirmed the HCV-induced epigenetic perturbations." (PMID 39209804, 2024). "Adult cholestatic liver disease samples had similar trends of the IRE1α/XBP1 and p-eIf2α -ATF4 expression suggesting that the UPR changes in the cholestatic liver groups may not be restricted to pediatric populations." (PMID 36520816, 2022). "The present study further supports the notion that the development of pharmacological inhibitors of the XBP1/NLRP3 pathway could present a new therapeutic strategy aimed at diminishing inflammatory liver diseases." (PMID 35842731, 2022). "UPR dysregulation, including the inositol-requiring enzyme 1α/X-box protein 1 (IRE1α/XBP1) pathway, is associated with adult liver diseases but has not been characterized in pediatric liver diseases." (PMID 36520816, 2022). "In order to determine whether the IRE1α/XBP1 pathway findings in pCLD explant samples were due to the effects of cholestasis and/or due to the advanced liver disease with extensive fibrosis, we next utilized explanted, cirrhotic livers from pediatric patients with AIH." (PMID 36520816, 2022). "Finally, adult cholestatic liver disease samples had similar trends of the IRE1α/XBP1 and p-eIf2α -ATF4 expression suggesting that the UPR changes in the cholestatic liver groups may not be restricted to pediatric populations." (PMID 36520816, 2022). "Thus, our findings suggest an effective strategy to prevent and/or treat liver inflammatory diseases by modulating the AMPK/SIRT1 pathway and targeting the XBP1/NLRP3 activity in macrophages using genetically modified MSC approaches or pharmacological interventions." (PMID 35842731, 2022).
lung adenocarcinoma (5 papers, 2017 to 2025). A carcinoma that arises from the lung and is characterized by the presence of malignant glandular epithelial cells. "In our study, we only observed splicing of mRNA encoding XBP-1 following treatment with known ER stress inducers including thapsigargin, ionomycin and tunicamycin in lung adenocarcinoma cell lines." (PMID 28186986, 2017). "Lu found that ER stress can induce the high expression of the transcription factor XBP1 in 2D and 3D culture lung adenocarcinoma cells and promote the proliferation of lung adenocarcinoma in 3D culture in vitro." (PMID 35559240, 2022). "Meanwhile, LOX gene, as a key downstream sensor of XBP1, can block XBP1-induced cell proliferation by knocking down the expression of LOX, suggesting that XBP1 can regulate the proliferation of lung adenocarcinoma cells through LOX." (PMID 35559240, 2022). "Interestingly, we also observed increased expression of CHOP and XBP-1 splicing at the mRNA level in primary lung adenocarcinoma compared to normal adjacent lung from the same patient." (PMID 28186986, 2017). "However, the role of XBP1 in lung adenocarcinoma (LUAD), especially the prognostic value of its alternative splicing isoforms, remains largely unknown." (PMID 36092910, 2022). "CPSF6-mediated shortening of the XBP1 3’ UTR alleviates cisplatin-induced ER stress and enhances chemoresistance in lung adenocarcinoma." (PMID 40544380, 2025).
periodontitis (5 papers, 2018 to 2025). An acute or chronic inflammatory process that affects the tissues that surround and support the teeth. "The levels of the four most highly up-regulated genes, IGLL5, SSR4, MZB1 and XBP1, were investigated in gingival RNA samples from ten subjects (six with periodontitis and four healthy controls)." (PMID 29921943, 2018). "The immunohistochemical analysis confirmed that SSR4, MZB1 and XBP1 proteins were expressed in gingival tissue from patients with periodontitis." (PMID 29921943, 2018). "Moreover, the expression of XBP1 has been confirmed to be upregulated in tissues affected by periodontitis." (PMID 36705422, 2023). "In the model of periodontitis induced by oral pseudomonas gingivalis in mice, 4-phenylbutyric acid (4-PBA, an ER stress inhibitor) reversed the significant expression of BIP, XBP1, total XBP1, CTSK, and TRAP genes and the increase in the osteoclast number and bone resorption in alveolar bone." (PMID 37509086, 2023).
anemia (4 papers, 2014 to 2022). A reduction in the number of red blood cells, the amount of hemoglobin, and/or the volume of packed red blood cells. "Loss of Xbp1 in Drosophila is embryonic lethal, and Xbp1-knockout mice develop hypoplastic livers and die in utero from anemia." (PMID 35049502, 2022). "The physiological significance of IRE1/XBP1 axis is highlighted by the findings that Ire1−/− and Xbp1−/− mice die embryonically due to liver failure, defects in the placenta, and anemia." (PMID 31817027, 2019). "XBP1 is essential for hepatocyte growth, as global knockout of XBP-1 embryos die in day 12.5 from severe liver hypoplasia and fetal anemia." (PMID 25530974, 2014).